DACT2 (dishevelled binding antagonist of beta catenin 2)
Diseases named in the same sentence as DACT2 in open-access papers (continued):
Sharing a sentence is not in itself a finding about the gene and the disease.
glioma (continued). "We showed that DACT2 is downregulated in glioma tissues and correlated with poor survival." (PMID 28796248, 2017). "Meanwhile, the present study provides evidence that DACT2 as a tumor suppressor gene could inhibit growth and induce apoptosis of glioma cells by suppressing YAP through Wnt/β-catenin signaling pathway." (PMID 28796248, 2017). "To test this hypothesis, we analyzed the expression of DACT2 and the clinicopathologic features through TCGA glioma data set, as well as the biological significance of DACT2 in glioma cell lines." (PMID 28796248, 2017). "In contrast, DACT2 knockdown promoted growth and enhance the weight of glioma." (PMID 28796248, 2017). "To determine whether YAP is involved in DACT2’s regulation of glioma cells proliferation and apoptosis, we performed rescue experiments." (PMID 28796248, 2017). "Data of TCGA also showed that expression of DACT2 was lower in higher grade glioma." (PMID 28796248, 2017). "The accurate mechanism that DACT2 regulates proliferation and apoptosis of glioma cells remains unclear." (PMID 28796248, 2017). "Furthermore, Univariate and multivariate analyses indicated that DACT2 was an independent prognostic factor for the OS of patients with glioma." (PMID 28796248, 2017). "Furthermore, the impact of DACT2 expression on the prognosis in gliomas patients was investigated by the TCGA data sets." (PMID 28796248, 2017). "We first examined the protein levels of DACT2 in 80 gliomas tissues and 10 normal brain tissues by immunohistochemistry (IHC), the result showed all normal brain tissues expressed DACT2 at higher levels, while glioma tissues with different grades showed apparently lower levels of DACT2 expression." (PMID 28796248, 2017). "Collectively, these data indicate that DACT2 has a tumor suppressor function via inactivation of YAP pathway, providing a promising target for the treatment of gliomas." (PMID 28796248, 2017). "The result demonstrated that DACT2 expression, WHO grade, KPS and age were independent prognostic parameters for glioma patients." (PMID 28796248, 2017). "Collectively, these data indicated that DACT2 has a negative effect on the growth of human glioma cells in vivo." (PMID 28796248, 2017).
lung carcinoma (4 papers, 2014 to 2023). "Additionally, DACT2 was reported to be frequently methylated in human lung cancer, and methylation of DACT2 was associated with poor differentiation of lung cancer." (PMID 35864965, 2022). "Recent studies further indicated that DACT2 could suppress Wnt signaling by inhibiting TCF/LEF in lung cancer." (PMID 27708215, 2016). "It is similar with our previous report in human lung cancer, the activity of TCF/LEF was increased by co-transfecting DACT2 and Dvl2 with wild-type or mutant-type β-catenin." (PMID 25375359, 2014).
lymph node metastasis (4 papers, 2014 to 2021). "DACT2 is frequently methylated in human papillary thyroid cancer and methylation of DACT2 is associated with lymph node metastasis." (PMID 25375359, 2014). "Methylation of DACT2 was associated with lymph node metastasis significantly (p<0.01)." (PMID 25375359, 2014).
nasopharyngeal carcinoma (4 papers, 2018 to 2022). A carcinoma arising from the nasopharyngeal epithelium. "In the study of nasopharyngeal carcinoma, it is found that the RAS association domain family 1A (RASSF1A) gene and disheveled-associated binding antagonist of β-catenin 2 (DACT2) promoter methylation can be used as markers for early auxiliary diagnosis." (PMID 35141222, 2022).
thyroid cancer (4 papers, 2014 to 2021). "The results suggest that methylation of DACT2 is associated with thyroid cancer metastasis." (PMID 25375359, 2014). "Aberrant methylation of SOX17 and DACT2, the key components of Wnt signaling, were found frequently in thyroid cancer." (PMID 34539742, 2021). "Epigenetic heterogeneity is found in four (CDH1, AP2, HIN1, and DACT2) of the five detected genes in thyroid cancer." (PMID 34539742, 2021). "The methylation of DACT2 was previously reported in lung and also in gastric and thyroid cancers where it correlated with tumor differentiation and invasion." (PMID 27553089, 2017). "DACT2 silencing by promoter region hypermethylation was detected in many tumor types including lung, gastric, hepatocellular and thyroid cancers." (PMID 26919254, 2016). "The results further suggest that DACT2 suppresses cell migration and invasion by inhibiting Wnt signaling in human thyroid cancer." (PMID 25375359, 2014). "To further understand the role of DACT2 in thyroid cancer, we detected the promoter region methylation in papillary thyroid cancer first." (PMID 25375359, 2014). "DACT2 expression was discovered in the human thyroid cancer cell line K1, SW579, FTC-133, TT, W3 and 8505C by regular PCR." (PMID 25375359, 2014). "Above results suggest that DACT2 suppresses thyroid cancer cell proliferation and metastasis by inhibiting Wnt signaling." (PMID 25375359, 2014). "DACT2 is frequently methylated in human lung, hepatic, gastric and thyroid cancers." (PMID 26919254, 2016). "DACT2 is reported to suppress lung, gastric and thyroid cancers by inhibiting Wnt signaling." (PMID 26919254, 2016). "It indicates that DACT2 inhibits cell invasion and migration in thyroid cancer." (PMID 25375359, 2014). "Five genes (AP2, CDH1, DACT2, HIN1, and RASSF1A) are found frequently methylated (>30%) in thyroid cancer." (PMID 34539742, 2021). "The results suggest that methylation of DACT2, HIN1, and RASSF1A increases the malignance of thyroid cancer." (PMID 34539742, 2021). "Five genes (AP2, CDH1, DACT2, HIN1, and RASSF1A) are methylated more than 30% in thyroid cancer." (PMID 34539742, 2021).
papillary thyroid cancer (3 papers, 2014 to 2022). "In order to explore the association of DACT2 expression and promoter region hypermethylation in primary papillary thyroid cancer, DACT2 expression was evaluated by immunohistochemistry (IHC) in 50 cases of available matched papillary thyroid cancer and adjacent tissue samples." (PMID 25375359, 2014). "The association of DACT2 methylation and clinical factors in 99 cases of papillary thyroid cancer." (PMID 25375359, 2014). "Another study revealed that DACT2 was repressed by promotor hypermethylation and pointed out the mediatory effect of DACT2 on papillary thyroid cancer proliferation and metastasis." (PMID 31894857, 2020). "We found that DACT2 expression was reduced in papillary thyroid cancer tissues compared with the adjacent tissue samples (p<0.001)." (PMID 25375359, 2014). "As DACT2 methylation is associated with papillary thyroid cancer metastasis, the effect of DACT2 on cell invasion and migration was analyzed in papillary thyroid cancer cells." (PMID 25375359, 2014). "In this study, we analyzed the epigenetic change and the function of DACT2 in papillary thyroid cancer." (PMID 25375359, 2014). "DACT2 suppresses cell proliferation and metastasis by inhibiting Wnt signaling in thyroid papillary cancer." (PMID 25375359, 2014). "In conclusion, DACT2 is frequently methylated in human papillary thyroid cancer and methylation of DACT2 is related to lymphoid node metastasis." (PMID 25375359, 2014). "In human primary papillary thyroid cancer, 64.6% (64/99) was methylated and methylation of DACT2 was related to lymph node metastasis (p<0.01)." (PMID 25375359, 2014). "It is possible to treat or prevent papillary thyroid cancer by targeting de-methylation of DACT2 to inhibit Wnt signaling." (PMID 25375359, 2014). "Above results indicate that methylation of DACT2 may serve as detective and metastatic marker of papillary thyroid cancer." (PMID 25375359, 2014). "In conclusion, DACT2 is frequently methylated in papillary thyroid cancer." (PMID 25375359, 2014). "As DACT2 expression was regulated by promoter region hypermethylation in papillary thyroid cancer, DACT2 methylation may involve in thyroid carcinogenesis." (PMID 25375359, 2014). "DACT2 suppresses papillary thyroid cancer proliferation and metastasis by inhibiting Wnt signaling." (PMID 25375359, 2014). "Hypoxia-induced exosomal miR-181a from papillary thyroid cancer targeted and inhibited MLL3, leading to the downregulation of DACT2, which contributed to tumor growth." (PMID 35864965, 2022).
breast tumor (2 papers, 2016 to 2022). "We further showed that Dvl2 and activated β-catenin were inhibited by DACT2 re-expression in breast tumor cells." (PMID 27708215, 2016). "Furthermore, ectopic expression of DACT2 induced breast cell apoptosis in vitro, and further inhibited breast tumor cell proliferation, migration and EMT, through antagonizing Wnt/β-catenin and Akt/GSK-3 signaling." (PMID 27708215, 2016). "We found that the expression of DACT2 mRNA in breast tumor specimens was significantly lower than that in non-tumor breast tissue specimens." (PMID 27708215, 2016).
colorectal tumors (2 papers, 2013 to 2016). "Although there have been relatively few reports about DACT2 in cancer research, the expression level of DACT2 appears to be reduced in some colorectal tumors." (PMID 23496880, 2013). "The expression level of DACT2 is reduced in some colorectal tumors." (PMID 27708215, 2016). "DACT2 is frequently downregulated by promoter methylation in HCC and colorectal tumors." (PMID 27708215, 2016).
esophageal squamous cell carcinoma (2 papers, 2016 to 2017). Esophageal squamous cell carcinoma (ESCC) is a type of esophageal carcinoma (EC) that can affect any part of the esophagus, but is usually located in the upper or middle third. "DACT2 remarkably suppressed TGF-β signaling via both proteasomal and lysosomal pathways in esophageal squamous cell carcinoma." (PMID 27708215, 2016). "High DACT2 protein levels were correlated with better differentiation and better survival rates in HCC and esophageal squamous cell carcinoma patients." (PMID 27708215, 2016).
liver cancer (2 papers, 2013 to 2016). An epithelial or non-epithelial malignant neoplasm that arises from the liver. "Of clinical significance, reduced DACT2 expression was significantly related to promoter hypermethylation in 28 of 62 (45.16%) HCC patients, and the expression of DACT2 was inversely related to β-catenin expression in liver cancers." (PMID 27556491, 2016). "Our study suggests that DACT2 is silenced by promoter hypermethylation, and reduced DACT2 can promote liver cancer progression." (PMID 23496880, 2013). "DACT2 transcripts were at low levels in hypermethylated liver cancer cells and were restored by exposure to a demethylating agent." (PMID 23496880, 2013). "We first detected the expression level of DACT2 in five liver cancer cell lines." (PMID 23496880, 2013). "5-Aza restored DACT2 expression in both cell lines with obvious demethylation observed in the treated HepG2 cell line by bisulfite genomic sequencing, suggesting that DNA methylation plays a crucial role in the transcriptional silencing of DACT2 in liver cancer cells." (PMID 23496880, 2013). "Taken together, these findings further support that DACT2 is inactivated epigenetically in a number of human solid tumors including HCC and that promoter hypermethylation may be a critical mechanism for the transcriptional silencing of the DACT2 gene in liver cancer cell lines." (PMID 23496880, 2013).
Obesity (2 papers, 2022 to 2026). Accumulation of substantial excess body fat. "As discussed, the actions of DACT2 in adipose tissue are not defined; furthermore, the dysregulation of Wnt signalling at study entry in individuals living with obesity may interfere with physiological DACT2 signalling." (PMID 35958557, 2022). "In addition, we report for the first time modulation of DACT2 mRNA expression by LC n-3 PUFAs which may have beneficial effects on dysregulated Wnt signalling in individuals living with obesity." (PMID 35958557, 2022). "Dact2 showed high significance and, as a TGFBR suppressor, may counteract the fibrosis observed in obesity, even if TGF-β remains unchanged." (PMID 41598416, 2026). "Elucidation of the role of DACT2 in adipogenesis may further our understanding of non-canonical Wnt signalling in obesity and how modulation by LC n-3 PUFAs affects adipogenesis in scWAT." (PMID 35958557, 2022).
head and neck carcinoma (1 paper, 2017). A carcinoma that arises from the head and neck region. "Further investigations should determine the detailed diagnostic significance of methylation of ZIC4, HHIP, and DACT2 in head and neck carcinomas." (PMID 27553089, 2017). "Further investigations should determine the diagnostic significance of methylation of ZIC4, HHIP, and DACT2 in head and neck carcinomas." (PMID 27553089, 2017). "On the other hand, we have observed that DACT2 is frequently methylated in both the cells lines and head and neck carcinomas while CXXC4 is methylated to a lesser extent." (PMID 27553089, 2017). "The analysis of the occurrence of gene promoter methylation in head and neck carcinoma cell lines indicated that CXXC4, DACT2, HHIP, ZIC1, and ZIC4 are methylated in these tumors." (PMID 27553089, 2017).
head and neck squamous cell carcinoma (1 paper, 2017). A squamous cell carcinoma that arises from any of the following anatomic sites: lip and oral cavity, nasal cavity, paranasal sinuses, pharynx, larynx, and salivary glands. "In summary, we report that CXXC4, DACT2, HHIP, ZIC1, and ZIC4 are methylated in head and neck squamous cell carcinomas." (PMID 27553089, 2017).
Hirsutism (1 paper, 2023). Abnormally increased hair growth referring to a male pattern of body hair (androgenic hair). "We found several differences in newborn methylation at individual CpG probes by maternal PCOS with reported hirsutism, though the difference in methylation near the DACT2 and MEOX1 genes may be due to downstream genetic control." (PMID 37992405, 2023).
liver diseases (1 paper, 2013). "It is therefore important to determine whether DACT2 still functions as a tumor suppressor gene in patients with other underlying liver diseases." (PMID 23496880, 2013).
thyroid (1 paper, 2014). "Above results suggest that DACT2 inhibits thyroid carcinogenesis and metastasis by inhibiting Wnt signaling pathway." (PMID 25375359, 2014).
tumor (22 papers, 2013 to 2025). "Metastasis research has focused on Dishevelled-associated antagonists of beta-catenin 2 (Dact2), which acts as a tumor suppressor." (PMID 37759472, 2023). "Overexpression of DACT2 inhibited the expression of β-catenin target genes associated with tumour growth and metastasis." (PMID 34997107, 2022). "AP2 methylation is associated with gender (P < 0.05), DACT2 methylation is associated with age, gender and tumor size (all P < 0.05), HIN1 methylation is associated to tumor size (P < 0.05) and extra-thyroidal extension (P < 0.01)." (PMID 34539742, 2021). "In GBM, decreased levels of DACT2 were proportionally associated with shorter patient survival, greater tumor aggressiveness and in vivo growth, suggesting that an apparent decrease in the levels of this protein favors tumor maintenance." (PMID 33312955, 2020). "Methylation of DACT2 was significantly associated with tumor stage and metastasis (P < 0.01, P < 0.05)." (PMID 26919254, 2016). "Methylation of DACT2 is significantly associated with tumor stage and metastasis." (PMID 26919254, 2016). "Reduced DACT2 expression was associated with large tumor size." (PMID 23496880, 2013). "Moreover, expression level of the DACT2 inversely associated with tumor grade." (PMID 28796248, 2017). "Therefore, DACT2 was implicated as a tumor suppressor gene in some types of human cancers." (PMID 23496880, 2013). "DACT2 suppresses tumor formation in xenografted mouse BRCA cells by inhibiting BRCA cell growth and inducing G1/S-phase blockage in BRCA cells." (PMID 40985028, 2025). "In concordance with the cell lines, SOSTDC1 and WIF1 were completely methylated but, DACT2 was hemi-methylated in tumours." (PMID 34997107, 2022). "DACT2 acts as a tumour suppressor by inhibiting canonical WNT signalling and is frequently silenced by promoter hypermethylation in BC." (PMID 34997107, 2022). "Further analysis find that methylation heterogeneity of AP2, DACT2, and HIN1 are associated with tumor size." (PMID 34539742, 2021). "This study also found that DACT2, regulated by kaempferol demethylation, reduced tumor load to some extent, indicating the potential of this compound for cancer therapy." (PMID 34235089, 2021). "Above results demonstrate that methylation heterogeneity of three genes (AP2, DACT2, and HIN1) is associated with tumor size." (PMID 34539742, 2021). "In contrast, Moonlight identified SOX7, CYP26B1, DACT2 as tumor suppressors with low expression in these same cell lines." (PMID 31900418, 2020). "Collectively, we conclude that TET1 exerts its anti-tumor functions in NPC cells by suppressing Wnt/β-catenin signaling via demethylation of Wnt antagonists (DACT2 and SFRP2)." (PMID 30075814, 2018). "In the relationship between DACT2 expression and the clinicopathological data, we found that DACT2 expression was negatively correlated with tumor size (P = 0.04)." (PMID 23496880, 2013). "Aberrant promoter hypermethylation of DACT2 was detected in several tumor samples with reduced DACT2 expression." (PMID 23496880, 2013). "Functionally, DACT2 is an important tumor suppressor gene with key roles of regulating tumor cell proliferation, migration and invasion in the development and progression of HCC." (PMID 23496880, 2013). "The high-expression group (n = 31) consisted of patients whose tumor tissue expressed DACT2 mRNA above the median value." (PMID 23496880, 2013). "To determine the role of DACT2 in tumor cell cycle progression and tumor cell proliferation, we examined the effect of DACT2 knockdown in MHCC97L cells on the cell cycle." (PMID 23496880, 2013). "Taken together, these results suggest the role of DACT2 as a functional tumor suppressor gene through suppressing tumor cell proliferation, migration and invasion in HCC." (PMID 23496880, 2013). "The low-expression group (30 samples) included patients whose tumor tissue expressed DACT2 mRNA below the median level." (PMID 23496880, 2013).